MMP9 (matrix metallopeptidase 9)
Diseases named in the same sentence as MMP9 in open-access papers (continued):
Sharing a sentence is not in itself a finding about the gene and the disease.
colorectal cancer (continued). "In the present study, we evaluated the association between, and the prognostic relevance of tissue protein levels of MMP-2 and MMP-9 and their gene promoter single-nucleotide polymorphisms (SNPs) in a cohort of 215 Dutch colorectal cancer patients." (PMID 18506186, 2008). "The prognostic significance of single-nucleotide polymorphisms (SNPs) and tumour protein levels of MMP-2 and MMP-9 was evaluated in 215 colorectal cancer patients." (PMID 18506186, 2008). "Earlier morphometric studies indicated that the degree of MMP-9 expression in tumour-associated lymphocytes, macrophages and neutrophils was inversely associated with invasion and metastasis in colorectal cancer." (PMID 18506186, 2008). "MMP-2 and MMP-9 have been implicated to play a role in colorectal cancer progression, invasion and metastasis in animal models and patients." (PMID 16916471, 2006). "Increased levels of an enzyme called matrix metalloproteinase 9 (MMP-9) have been found to be associated with colorectal cancer, and this can be measured from a blood sample." (PMID 17076885, 2006). "In the present study, we analysed the cellular enzymatic expression of MMP-9 in 18 human colorectal cancer (CRC) liver metastasis specimens by enzyme-linked immunosorbent assay (ELISA) and zymography." (PMID 9703281, 1998). "Others, such as MMP9 29, were associated with the metastasis of colorectal cancer." (PMID 32922546, 2020). "MMP9 has potential for detecting those at risk of having colorectal cancer." (PMID 19175925, 2009). "Collectively, these data suggest that selective MMP9 inhibition is a promising therapeutic strategy for treatment of inflammatory and oncology indications in which MMP9 is upregulated and is associated with disease pathology, such as ulcerative colitis and colorectal cancer." (PMID 25961845, 2015). "In conclusion, this study shows that increased MMP-2 and MMP-9 protein expression in normal mucosa at some distance of colorectal tumours is strongly related to the course of disease, that is, independently associated with a poor prognosis of colorectal cancer patients." (PMID 22472880, 2012). "Previous studies have shown that neutrophil-secreted MMP-9 can degrade collagen and promote neutrophil migration in lungs and colorectal cancer models." (PMID 40185981, 2025). "Olaparib alone reduced mRNA expression levels of MMP2 and MMP9 in oral carcinoma cell lines and, combined with bevacizumab, was found to reduce the serum levels of MMP9 in advanced colorectal cancer." (PMID 39859407, 2025). "Due to the recognized functions of MMP-2 and MMP-9 in extracellular matrix degradation and colorectal cancer progression, these gelatinases were chosen for examination." (PMID 41154590, 2025). "Mechanistically, matrix metalloproteinase 9 (MMP-9) from neutrophils can stimulate angiogenesis in vitro, and using MMP-9 knockout mice, a direct relationship was found between neutrophil MMP-9 and increased tumor angiogenesis in a colorectal cancer model." (PMID 39653768, 2025). "In colorectal cancer studies, ADM expression has been positively correlated with MMP-9 expression, and their combined activity has been shown to enhance the migration and invasion of colorectal cancer cells." (PMID 40565016, 2025). "This study suggests that newly synthesized depside compounds suppress the progression of colorectal cancer by directly targeting VDAC1/PHB/MMP9." (PMID 41179704, 2025). "Exosomal ANGPTL1 reprograms Kupffer cells and reduces their MMP9 expression, averting hepatic vascular leakage and impeding colorectal cancer liver metastases." (PMID 40475773, 2025). "Specifically, METTL3-induced m6A methylation of Matrix metallopeptidase 9 (MMP9) mRNA can promote colorectal cancer proliferation." (PMID 40986143, 2025). "Collectively, these findings demonstrate that SB4 and SB5 are promising candidates for colorectal cancer therapy by targeting VDAC1/PHB/MMP9." (PMID 41179704, 2025).
colorectal cancer (continued). "In colorectal carcinoma tissue and the adjacent tissue, significantly increased expression of NF-κB, higher concentrations of AOPPs, and enhanced MMP-9 activity were observed." (PMID 40729026, 2025). "Supporting this, evidence from in-vitro studies demonstrates how colorectal cancer cell lines can trigger MMP9 production in monocytes through a membrane barrier, illustrating the non-direct communication within the tumor microenvironment." (PMID 39664453, 2024). "In colorectal cancer, resveratrol (5 μM) reduced the MMP-9 protein level by modulating the cellular response to TNF-β and downregulating the NF-κB pathway." (PMID 39335164, 2024). "MMP9 contributes to various phases of colorectal cancer progression, including invasion, EMT, and angiogenesis." (PMID 38808892, 2024). "MMP9 plays a critical role in both inflammation and tissue remodeling, processes fundamental to the development of colorectal cancer and neuronal damage." (PMID 39664453, 2024). "NGR1 can inhibit the invasion and metastasis of colorectal cancer cells by inhibiting the expression of MMP9." (PMID 38885076, 2024). "NGR1 can inhibit the invasion and metastasis of colorectal cancer cells by inhibiting MMP9 expression." (PMID 38885076, 2024). "Based on the preceding discussion, the role of MMP9 in colorectal cancer pathogenesis is central to understanding the disease’s aggressive nature." (PMID 39664453, 2024). "It has been demonstrated that the JAK2/STAT3 signaling pathway is involved in the regulation of MMP9 expression in colorectal cancer." (PMID 39664453, 2024). "In another study, quercetin in combination with Lycopodium clavatum extract resulted in a significant downregulation of MMP-2 and MMP-9 activities, as tested by gelatin zymography in colorectal cancer Colo-320 cells." (PMID 39683504, 2024). "This review aims to assess the role of MMP9 in the progression of colorectal cancer (CRC) and the development of chemotherapy-induced peripheral neuropathy (CIPN)." (PMID 39664453, 2024). "Similar results were also obtained in the case of GEN (10, 20, and 60 μM) which dose-dependently reduced the expression of both MMP-2 and MMP-9 in HT-29 colorectal cancer cells after 72 h of treatment." (PMID 38792627, 2024). "The inhibition of PI3K/Akt/NF-κB pathway, EMT and MMP-9 activity are critical events in antimetastasis effect of 5-FU/parecoxib combination in colorectal cancer." (PMID 39062099, 2024). "For example, CXCL10 induced by IFNγ contributes to invasion and metastasis in human colorectal carcinoma by induction of matrix metalloproteinase 9 (MMP9)." (PMID 38786066, 2024). "Our method introduced SPATA13 a guanine-factor as a novel amplification driver gene in colorectal carcinoma, required for MMP9 up-regulation via the JNK signaling pathway in colorectal tumor cells." (PMID 38195844, 2024). "Expression of MMP-9 and NF-κB were also reported to be decreased in colorectal cancer cells and paclitaxel-resistant colorectal cancer cell lines (HCT116, LoVo and CT26) with ATRA treatment." (PMID 38069361, 2023). "TANs can suppress the immune system by activating TGFβ with their MMP9 secretion in colorectal cancer." (PMID 37376417, 2023). "Increased expression of MMP-9 in colorectal cancer tissue has been demonstrated, correlating with the stage of disease advancement, greater invasiveness and shorter survival time of patients." (PMID 37895400, 2023). "MnTE-2-PyP inhibited the Smad2/3 signaling pathway and the expression of matrix metalloproteinase 2 (MMP-2) and 9 (MMP-9) in colorectal cancer cells, reducing TGF-β-induced EMT and thus invasion of the colorectal and other cancer cells." (PMID 37049670, 2023). "Enalapril, an antihypertensive medication, can re-sensitize colorectal cancer cells to 5-fluorouracil chemotherapy by inhibiting NF-kB and reducing MMP-9, a pro-angiogenic molecule released in NETosis." (PMID 37143649, 2023).
colorectal cancer (continued). "KDM3A/B substantially regulates the expression of Wnt or beta-catenin target genes c-Myc, MMP9 (matrix metallopeptidase 9), and cyclin D1 in colorectal cancer, thereby promoting the ability of colorectal cancer stem cells to undergo self-renewal." (PMID 37218871, 2023). "Gomisin A can also reduce the levels and activities of matrix metalloproteinase (MMP)-2 and MMP-9, and improve the lung metastasis of colorectal cancer cells by reducing the cell survival and metastasis ability of colorectal cancer cells." (PMID 37560060, 2023). "The humanized monoclonal antibody GS-5745, a potent and highly selective allosteric MMP9 inhibitor, has been developed for clinical trials in ulcerative colitis and colorectal cancer." (PMID 36250005, 2022). "In this work, we investigated the anti-tumor role of deflamin, a protein oligomer isolated from white lupine seeds (Lupinus albus) reported to inhibit MMP-9 and cell migration in colorectal cancer (CRC) cell lines." (PMID 36551666, 2022). "Previous evidence has indicated that MMP2 and MMP9 are two important genes that are closely related to the migration of tumor cells, including colorectal cancer." (PMID 34974798, 2022). "Cholic acid enhances the invasion of colorectal cancer cells by activating mmp9-related signaling pathways." (PMID 36160256, 2022). "The present study revealed that MYL9 deletion downregulated the expression of MMP2 and MMP9 while MYL9 overexpression upregulated the expression of MMP2 and MMP9 in colorectal cancer cells." (PMID 34974798, 2022). "miR-153-induced dug resistance of cancer cells is promoted by production of matrix metalloproteinase (MMP9) as well as inhibiting transcription factor Forkhead box class O 3a (FOXO3a), a tumor suppressor protein in colorectal cancer." (PMID 36158686, 2022). "MMP9 was significantly positively correlated with PD-L1 and promoted poor prognosis in patients with tongue squamous cell carcinoma and colorectal cancer." (PMID 36189226, 2022). "The present study showed that E-cadherin (as an epithelial marker) is down-regulated whereas concomitantly N-cadherin, vimentin, and MMP-9 (as mesenchymal markers) are up-regulated in colorectal cancer." (PMID 34094030, 2021). "MMP-2 and MMP-9 are known as type IV collagenase and are increased in CRC patients and are associated with colorectal cancer progression." (PMID 34502094, 2021). "As in different type of diseases, MMP-9 was higher (e.g., in colorectal cancer, ulcerative colitis, and inflammatory bowel diseases)." (PMID 34458302, 2021). "Sevoflurane and desflurane inhibited cell invasion through MMP9 downregulation in colorectal cancer cells." (PMID 33919449, 2021). "Results showed that ROCK1, LIMK1, MMP3, and MMP9 mRNA expressions were down-regulated after ALKAL1 silencing in colorectal cancer RKO and SW480 cells." (PMID 33391411, 2021). "In colorectal cancer, the co-culture of tumor associated macrophages and colorectal cancer cells elevates the generation of cancer-derived MMP-2 and MMP-9." (PMID 33043017, 2020). "It is expected to estimate illness progression and treatment of patients with colorectal cancer by detecting IL-17, MMP-9 and CD23 in the future." (PMID 32461933, 2020). "According to existing studies, MMP-2 and MMP-9 are overexpressed in colorectal cancer, and MMP-9 is a poor prognostic factor in preoperative CRT response of LARC patients." (PMID 32351671, 2020). "MMP-9, known as gelatinase B, specifically in colorectal cancer, appears as a protease that regulates tumor cell growth, mobility and survival." (PMID 32813775, 2020). "The result is consistent with promotion of cell migration and invasion MMP-9 through the Jak2/Stat3/MMP9 signaling pathway in B7‐H3 stimulation in colorectal cancer." (PMID 33228717, 2020).
colorectal cancer (continued). "MMP-9 inhibitors (MMPIs) are considered metastasis deterrents and anti-angiogenic agents for colorectal cancer, and have also been proved to inhibit pre-cancerous states like colitis and other inflammatory bowel diseases." (PMID 33308217, 2020). "In another study, the inhibitory effect of non-cytotoxic concentrations of free DTX on down-regulation of MMP9 was observed in colorectal cancer cells." (PMID 30041514, 2019). "Excessive degradation of the matrix is one of the hallmarks of metastasis, and uPA, MMP-2, and MMP-9 play a role in human colorectal cancer progression, invasion, and metastasis." (PMID 31511625, 2019). "The expression of the gelatinases MMP-2 and MMP-9 is increased in colorectal cancer tissues when compared to concomitant normal tissues." (PMID 30931081, 2019). "Meanwhile, real-time qRT-PCR and western blot assays indicate that MnTE-2-PyP inhibits TGF-β-induced MMP-2 and MMP-9 in colorectal cancer cells." (PMID 30931081, 2019). "Accumulating evidence indicates that MMP9 is critical for migration and invasion of cancerous cells including triple-negative breast cancer and colorectal cancer." (PMID 31526394, 2019). "MnTE-2-PyP effectively suppressed TGF-β-induced cell migration and invasion and the expression of matrix metalloproteinase 2 (MMP-2) and matrix metalloproteinase 9 (MMP-9) in colorectal cancer cells." (PMID 30931081, 2019). "By tissue sampling, the overexpression of MMP-9 has also been detected by immunohistochemical assays using micro-RNA and labelled IgG in different types of cancer such as colorectal carcinoma, and breast cancer." (PMID 31426440, 2019). "Immunohistochemical results have exhibited that overexpression of MMP-9 correlates with poor outcome as evaluated by disease-free survival in colorectal carcinoma." (PMID 33817161, 2019). "Supporting this, in DLD1 and HCT116 human colorectal carcinoma, recruited human patrolling monocytes in tumors secrete matrix metalloproteinase 9 (MMP9), a proteolytic enzyme fostering angiogenesis, triggering a release of matrix-bound VEGFA." (PMID 31474975, 2019). "All in all, MMP-8 and TIMP-1 seem to influence the prognosis of colorectal cancer patients to a greater extent than MMP-9 seems to do." (PMID 29929486, 2018). "In preclinical models, selective MMP-9 inhibitors have been shown to decrease tumor growth and the incidence of metastases in colorectal cancer and also induce cancer cell apoptosis in pancreatic cancer." (PMID 29520667, 2018). "Among 26 stage III colorectal cancer patients, levels of MMP-9 and IL-8 were significantly elevated and correlated with each other." (PMID 29929486, 2018). "Our results showed that there is strong association between MMP-9 and CRP serum levels and progression of colorectal cancer." (PMID 30154846, 2018). "In contrast, in a study on 180 patients, of whom 75 had colorectal cancer, MMP-9 and TIMP-1 levels were higher in colorectal cancer patients than in healthy controls or in colorectal adenoma patients." (PMID 29929486, 2018). "Recent publications about colorectal cancer indicate that matrix metalloproteinase-9 (MMP-9) serum levels are elevated in the patients with colorectal cancer." (PMID 30154846, 2018). "The aim of this study to evaluate mutual relation between IL-6, CRP and MMP-9 serum levels in patients with CRC and their association with staging and clinical-pathological features of colorectal cancer." (PMID 30154846, 2018). "Plasma MMP-9 levels are significantly raised in patients with colorectal cancer and also decrease after tumor resection, suggesting MMP’s potential as a prognostic and diagnostic biomarker." (PMID 29520667, 2018). "Uc.338 is an important oncogene which increased expression of MMP9 to improve invasion and migration of cancer cells in colorectal carcinoma, low- expression of uc.73 closely related with stage and grade of colorectal neoplasia." (PMID 29484123, 2018).
colorectal cancer (continued). "It has recently also been reported that overexpression of Nur77 promotes colorectal cancer cell invasion and metastasis through regulation of MMP-9-dependent E-cadherin reduction." (PMID 28170411, 2017). "For example, overexpression of Nur77 in colorectal cancer promotes cancer cell invasion and metastasis by regulating MMP-9-dependent E-cadherin reduction." (PMID 28170411, 2017). "It has been observed that MMP9 hemopexin domain has an inhibitory effect on migration and adhesion of colorectal carcinoma cells." (PMID 27861153, 2017). "We recently also reported that Nur77, an orphan member of the nuclear receptor superfamily, induces E-cadherin reduction in a Matrix metalloproteinase 9 (MMP-9)-dependent manner, and subsequently contributes to the invasion and metastasis of colorectal cancer." (PMID 27756432, 2016). "The increased MMP-9 is involved in cell migration and invasion in colorectal cancer and acute leukemia." (PMID 27036041, 2016). "B7-H3 was expressed in the cancer cell membrane and was associated with the T stage of colorectal cancer; it also showed a positive correlation with MMP2 and MMP9 expression in cancer tissues." (PMID 27145365, 2016). "The results pointed to FOXM1 facilitated the activities of MMP2 and MMP9 at least partly dependent on cell-surface HSPA in colorectal cancer cells." (PMID 27034162, 2016). "We recently reported that upregulation of Nur77, an orphan member of the nuclear receptor superfamily, confers colorectal cancer invasive features through regulating MMP-9-dependent E-cadherin reduction." (PMID 27756432, 2016). "Nevertheless, baseline serum levels of LCN2 and MMP9 (as determined by the ELISA measurements) in 24 cases were similar to previously reported values in patients with colorectal cancer and considerably higher than those in healthy subjects." (PMID 27461255, 2016). "In a study of primarily resected colorectal cancers, primary tumor MMP9 expression was an independent predictor of disease-free survival." (PMID 27461255, 2016). "Wnt3a expression is significantly associated with lymph node involvement and matrix metallopeptidase-9 (MMP-9) expression in primary tumor, mesenchyme adjacent to tumor, and metastatic sites in colorectal cancer." (PMID 26369691, 2015). "Collectively, these data support the therapeutic promise of an anti-MMP9 antibody in ulcerative colitis and colorectal cancer." (PMID 25961845, 2015). "The oncogenic role of CCL20 has been characterized to be the promotion of tumor cell invasion through the up-regulation of MMP-9 in colorectal cancer cells and pancreatic adenocarcinoma." (PMID 26300991, 2015). "We also found that MMP9 inhibition decreased tumor growth and metastases incidence in a surgical orthotopic xenograft model of colorectal carcinoma, and that inhibition of either tumor- or stroma-derived MMP9 was sufficient to reduce primary tumor growth." (PMID 25961845, 2015). "Regarding MMP9 expression in colorectal cancer tissues, mean value of immune-expression was 1.39±1.77 (SD) and median value was 1 (range, 0–8)." (PMID 24504172, 2014). "This is seen by its inhibitory effect on the migration and invasion of colorectal cancer cells, and on actions achieved by down-regulating the activities of MMP9, via an ERK dependent pathway." (PMID 25260785, 2014). "The expressions between CTHRC1 and MMP9 in colorectal cancer tissues revealed the weak correlations." (PMID 24504172, 2014). "The expressions of MMP9 was weakly correlated to the expressions if CTHRC1 in colorectal cancer tissue (R=0.171, p=0.019)." (PMID 24504172, 2014). "In accordance with the Human Protein Atlas and a review of the literature, human colorectal carcinoma was used as a positive control to assess the levels of MMP-9 expression in human cancers." (PMID 25151367, 2014).